CXCR4 (C-X-C motif chemokine receptor 4)
Diseases named in the same sentence as CXCR4 in open-access papers (continued):
Sharing a sentence is not in itself a finding about the gene and the disease.
breast tumor (continued). "Taken together our results indicate that CAFs exposed to BRL acquired a phenotype characterized by an altered morphology, a decreased expression of CXCR4 and inhibited migratory capabilities, all features that may negatively impact breast tumor progression." (PMID 27556298, 2016). "We conclude that tumor cell-derived ANGPTL2 may increase bone metastasis by enhancing breast tumor cell responsiveness to CXCL12 signaling through up-regulation of tumor cell CXCR4 expression." (PMID 25773070, 2015). "It is reasonable that the role of CXCR4 in breast tumors might involve more than positive and higher expression levels in tumoral cells." (PMID 26161302, 2015). "Mechanistically, NCOA1 has been shown to up-regulate Twist1, ITGA5, CSF-1, SDF1 and CXCR4 expression, which are partially responsible for promoting metastasis through potentiating breast tumor cell epithelial-mesenchymal transition (EMT), migration, invasion and macrophage recruitment." (PMID 26287601, 2015). "We used a model based on CXCR4-transfected culture to analyze the role of exosomes released from breast tumor cells with different stemness/metastasis abilities in the capacities for tumor growth, generation of stem cell features in neighboring cells, and metastatic potential." (PMID 26528758, 2015). "Finally, this work showed increased CXCR4 expression in breast tumor tissues, at both mRNA and protein levels, but this increase is not influenced by rs2228014 genetic polymorphism." (PMID 26576337, 2015). "Since CXCR4 has both functional and prognostic significance for metastasis in breast tumors and cells, the antimetastatic activity of omeprazole and other AHR-active pharmaceuticals including other benzimidazole protein pump inhibitors are currently being investigated." (PMID 25011475, 2014). "Finally, anti-metastatic activity of BD in vivo was further confirmed by the downregulation of expression of PLAU (urokinase plasminogen activator, uPA) and CXCR4 (C-X-C chemokine receptor-4) genes in breast tumors." (PMID 22842551, 2012). "The expression pattern of CXCR4 in four breast tumor cell lines was evaluated using RT-PCR." (PMID 22220212, 2011). "In this study, we report that a synthetic non-psychoactive cannabinoid that specifically binds to cannabinoid receptor CB2 may modulate breast tumor growth and metastasis by inhibiting signaling of the chemokine receptor CXCR4 and its ligand CXCL12." (PMID 21915267, 2011). "Since CXCL12 is expressed preferentially in lymph nodes, this may support our data that CXCR4 expression was significantly correlated with lymph node metastasis in human breast tumor samples." (PMID 19025611, 2008). "Furthermore, CXCR4 has been reported to be upregulated in breast tumors." (PMID 30486409, 2018). "Chemokine CXCL12 expressed in the brain and its counter-receptor CXCR4, which is present on the surface of breast tumor cells, have been suggested to play essential roles in tumor cell migration in the brain that could be prevented by blocking the CXCR4-dependent intracellular pathway." (PMID 26781299, 2016). "Given that increased stem cell biomarker expression was observed in high NOS2 expressing ER- breast tumors, we measured CSC biomarker expressions (ALDH1A1, OCT4, CXCR4, CD133, CD117, CD44 and NANOG) in the control and DETANO treated MCF10A cells." (PMID 36830680, 2023). "High levels of CXCR4 levels were expressed in more than 40% of breast tumor tissues and in 75% of TNBC patients, and overexpression of CXCR4 in cancer cells contributes to tumor growth, invasion, metastasis, and recurrence." (PMID 38111587, 2023). "We also found that there were increased Pdl1 and Pd1 staining in breast tumor tissues from Brca1Co/Co;MMTV-Cre treated either with Tas for S100A9 or AMD3465 which is an inhibitor for CXCR4, a receptor for CXCL12." (PMID 35304461, 2022). "Elevated production of functional MMP2 and MMP9 was detected in breast tumor cells following CXCL12 stimulation, in the context of CXCR4 expression." (PMID 32582148, 2020).
breast tumor (continued). "Signaling through CXCR4 activates the PI3K/AKT pathway, which is involved in the initiation and progression of breast tumors and regulates various cellular functions, including survival, proliferation, and metabolism." (PMID 32047724, 2019). "It is conceivable that inflammation and/or angiogenesis in the tumor microenvironment contributes to the activation of CXCR4 and PTGS2 in MDMX-overexpressing breast tumor cells." (PMID 30642351, 2019). "Based in many in vitro and in vivo evidences, nowadays, it is widely accepted that CXCR4/CXCL12 axis is involved in tumor growth, migration and invasion of human breast tumor cells." (PMID 30012106, 2018). "Recently, it was demonstrated that stroma cells of breast tumors synthesize the chemokine SDF-1, which via its cognate receptor (CXCR4) supports tumor growth through autocrine and paracrine mechanisms." (PMID 29285291, 2017). "Interestingly, our data showed that CAFs exposed to the treatment with the PPARγ agonist BRL acquired a phenotype characterized by a decreased expression of α-SMA/vimentin and CXCR4 together with a reduced migratory capability, all features that may negatively impact breast tumor progression." (PMID 27556298, 2016). "We also found that ETS1-dependent transcription was important for ANGPTL2-induced CXCR4 expression and that ANGPTL2 increased breast tumor cell invasiveness by activating ERK and MMP-13 expression." (PMID 25773070, 2015). "More recent data indicated that in addition to CXCR4 and CCR7 and its ligands also EGFR was significantly higher expressed in breast tumor cells with lymph node metastasis, which was correlated to shorter survival period of afflicted patients." (PMID 23667660, 2013). "Similar to CXCR4, CCR7-CCL21 interactions induces directional invasion of breast tumor cells, pseudopodia formation, and actin polymerization which increases the invasiveness of tumor cells." (PMID 24259307, 2013). "Second, we examined the mechanistic basis of the differences in breast tumour cell responses to TSA, depending on tumour aggressiveness, and considered the transcriptional regulation of CXCR4 and Met, two genes important for tumour cell invasiveness." (PMID 18941460, 2008). "TGF-β not only induced tumour cell migration through the EMT process, but also increased the CXCR4 expressions in 4T1 tumour cells, which combined with CXCL12 to activate intracellular PI3K/Akt pathway, promoting the occurrence and metastasis of breast tumours." (PMID 37162544, 2023). "Thus, breast tumors generated by MMTV-neu:FAAH−/− mice expressed higher mRNA and protein levels of Cxcr4 and Cxcl12 than their FAAH-expressing counterparts, which is consistent with their enhanced aggressive behavior and metastatic rate." (PMID 37253733, 2023). "On one hand, it was found that the expression of CXCR7/ACKR3 by breast tumor cells has provided growth advantages to luminal breast tumor cells (at times even when CXCR4 was not active in this respect), and reduced trail-mediated apoptosis in such cells." (PMID 32582148, 2020). "HER-2-negative breast tumors with an overexpression of CXCR4 demonstrate more aggressive behavior and are more likely to recur than tumors that do not express elevated levels of CXCR4." (PMID 26848769, 2016). "In the present study, we performed RNA sequence analysis of MDA-MB231 cells harboring ANGPTL2 knockdown (MB231/miANGPTL2) and found that, relative to control (MB231/miLacZ) cells, CXCR4 expression significantly decreased, suggesting that ANGPTL2 contributes to CXCR4 expression in breast tumor cells." (PMID 25773070, 2015). "High levels of CCR7 are consistently expressed in breast tumor cells along with CXCR4, though CCR7 is also expressed in normal mammary epithelial cells." (PMID 24259307, 2013). "We found a 1.5-fold increase in gene expression of the metastatic marker CXCR4 in breast tumors from runners compared with non-runners (p = 0.04)." (PMID 24312199, 2013).
breast tumor (continued). "The MDA-MB-435 breast tumor cell line showed a methylated fragment in the CXCR4 CpG island, which correlated with the lack of CXCR4 expression in this cell line." (PMID 22220212, 2011). "Furthermore, TNMplot database also pinpointed a negative correlation between MEG3 and CXCR4 expression in breast tumor samples." (PMID 40548301, 2025). "Interestingly, the expression of CXCL12 and its receptor C-X-C motif chemokine receptor 4 (CXCR4) is increased by hypoxia, which could further promote Treg infiltration in breast tumours, especially in the basal-like subtype." (PMID 34769447, 2021). "However, another study demonstrated different roles for CXCR4 and CXCR7/ACKR3 in regulating estrogen-dependent growth of luminal breast tumor cells, where CXCR4 enhanced cancer cell growth and CXCR7/ACKR3 over-expression inhibited cell proliferation, possibly through CXCL12 sequestration." (PMID 32582148, 2020). "Hence, CXCR4 as well as GRK3 could be used as biomarkers, not only for the diagnosis of breast tumors but also to define phenotypes and evaluate metastatic risks." (PMID 30513833, 2018). "Because CXCR4 was known to mediate proliferation, invasion and metastasis of tumour cells, in this study, we investigated whether TPD7 could modulate the expression of CXCR4 and thus inhibited breast tumour cell proliferation and invasion." (PMID 25753200, 2015). "Of note, analysis of a publicly available gene expression database demonstrated that it is not the high individual expression of CXCR4 and CCR7, but their enhanced co-expression levels that significantly correlate with the increase in breast tumour grade." (PMID 34685420, 2021). "We reported that the breast tumor cell line MDA-MB468, which does not express CXCR4, is refractory to Nef-M1-induced apoptosis." (PMID 26318034, 2015). "The expression profiles of CXCR4, CXCR7, CXCL12, and COUP-TFI mRNA in 82 breast tumors and control non-tumor samples were measured using real-time PCR." (PMID 24906407, 2014).
viral infection (79 papers, 2005 to 2025). "In pathological contexts, CXCR4 is implicated in both cancer development and progression, as well as viral infections, particularly in the case of HIV-1, where CXCR4 serves as the coreceptor for CD4 on T cells during infection." (PMID 38519141, 2024). "The information obtained from these analyses can guide the development of new therapeutics for diseases that involve CXCR4, particularly those caused by viral infections." (PMID 36992255, 2023). "Expression of cell receptors (such as IFNGR1 and CXCR4) was reduced by a viral infection and is associated with suppression of associated signaling pathways and immune function." (PMID 36163484, 2022). "The only factor associated with a CXCR4-using virus infection in multivariate analysis was the nadir of CD4 cells: <200/mm3 (OR: 3.94, 95%CI: 1.39–11.14)." (PMID 23226258, 2012). "Interestingly, the expression of cell receptors, such as IFNGR1 and CXCR4, was reduced in response to the viral infection and associated with the inhibition of the related signaling pathways and immune functions." (PMID 34944610, 2021). "In conclusion, our work demonstrates that knockdown of both CIB1 and CIB2 impaired an early step in receptor-mediated viral entry involved in both cell-free and cell-mediated viral infection, and was associated with reduced surface expression of CXCR4, CCR5 and α4β7." (PMID 27489023, 2016). "C-X-C motif chemokine receptor 4 (CXCR4) is a protein that plays a pivotal role in both cancer progression and viral diseases." (PMID 40278256, 2025). "Our results from viral entry assay and VSV-G pseudotyped virus infection confirmed that the inhibition of CXCR4-mediated viral entry is the primary mechanism of action of TIQ-15." (PMID 39146384, 2024). "Regarding alveolar and interstitial macrophages, or blood-derived arriving macrophages, Mtb induces the expression of both coreceptors for HIV CCR5 and CXCR4, promoting viral infection in these host cells and the consequent expansion of viral reservoirs." (PMID 37110276, 2023). "High levels of CCL2 can assist viral infection by recruiting target cells to affected sites and increasing the expression of CXCR4 (a co-receptor for HIV)." (PMID 37999614, 2023). "Among the chemokine receptors, CXCR4 stands out for its pleiotropic roles in several pathological conditions, including immune diseases, viral infections and cancers." (PMID 35795203, 2022). "This contrasts with our previous phenotypic determination of X4-1 Env viral tropism based on cell-free virus infection of U87-CD4 reporter cells expressing CCR5 or CXCR4 that indicated exclusive usage of CXCR4 by this Env." (PMID 35622876, 2022). "In viral infections, SARS-CoV-2, hCoV-229E, or HIV activate Panx1 hemichannels via CD4/CXCR4 CD4/CCR5, causing an outflow of ATP, which induces the maturation of IL-1ß through the activation of P2X7 receptors." (PMID 36699007, 2022). "Additional experiments to evaluate the impact of TFR on CCR5-tropic HIV GFP reporter virus expression revealed a similar magnitude of TFR-mediated suppression of HIV replication as seen in CXCR4-tropic HIV GFP reporter virus infection." (PMID 36420277, 2022). "Following viral infection with CXCR4-tropic NL4-3 or CCR5-tropic THRO.c/2626, the transduced cells exhibited gradually increased percentages of GFP-positive (GFP+) cells over time." (PMID 33462383, 2021). "When IgE-FcεRI aggregation was induced by HIV gp120 or antigen from Schistosoma mansoni eggs, the expression of CXCR4 in MC precursors was up-regulated, increasing their susceptibility to X4 and R5X4 virus infection." (PMID 34211473, 2021). "Specifically, CXCR4 has multifunctional effects, and is widely involved in a variety of pathological conditions, including immune diseases, viral infections and cancer." (PMID 33795012, 2021).
viral infection (continued). "In this line, MC precursors cultured in vitro from fetal or adult CD34+ progenitors co-expressed CD4, CXCR4, and CCR5 and were susceptible to R5 tropism in viral infection, but only marginally susceptible to X4-HIV infection." (PMID 34211473, 2021). "We hence conducted pseudotyped virus infection studies in the presence of AMD3100 (CXCR4 antagonist), Maraviroc (CCR5 antagonist) or a combination of both to determine the co-receptor preference of the two Envs." (PMID 31581579, 2019). "Since, there is increasing evidence that abnormal expression and genetic variation of CXCR4 is involved in several pathological conditions, including immune diseases, viral infections, multiple cancers, and cardiovascular diseases." (PMID 29581828, 2018). "Replacing MPR with the corresponding region from CCR3, CCR2b, or CXCR4 significantly abolishes viral infection." (PMID 28484468, 2017). "Previous studies have shown that the interaction between recombinant gp120 and CD4/coreceptors (CCR5 or CXCR4) enhances the early stage of viral infection." (PMID 28842659, 2017). "CCR5 virus infections produced extensive proviral diversity while in CXCR4 infections a more localized substitution process was observed." (PMID 26413773, 2015). "This is consistent with the notion that evolution of the viral infection to produce HIV-1 strains that can readily utilize CXCR4+ cells, either in the plasma or gut tissue compartments, herald rapid disease progression to death." (PMID 24146801, 2013). "These human immune cells are susceptible to HIV infection by both CXCR4 utilizing and CCR5 utilizing strains and can support virus infection for several months." (PMID 23202514, 2012). "Taken together, our results suggest that CB2 cross-regulates CXCR4 and that this inhibitory cross-talk is sufficient to decrease viral infection." (PMID 22448282, 2012). "The data indicate that SIL caused a generalized suppression of T cell expansion, resulting in fewer target cells with CD4 and CXCR4 and/or CCR5 that are susceptible to virus infection." (PMID 22848626, 2012). "Upon viral infection, CXCR4 transcript levels were effectively repressed in cells infected with both type 1 and type 2 EBNA-2 recombinant EB viruses." (PMID 21857817, 2011). "By inactivating CXCR4 singly and in combination with CCR5, it will be possible to study the effects of CXCR4 loss on T cell function as well as virus infection in a more relevant animal model." (PMID 21533216, 2011). "Nevertheless, the in vivo importance of these other coreceptors in viral infection and pathogenesis is less studied than that of CXCR4 and CCR5." (PMID 20041213, 2009). "The siRNA genes against HIV-1 coreceptors CCR5 and CXCR4 are able to downregulate the respective cell surface proteins and thus confer resistance against viral infection by restricting viral entry." (PMID 18667075, 2008). "Stable simultaneous knock down of the HIV-1 coreceptors CCR5 and CXCR4 is a promising strategy to protect cells from both R5 macrophage tropic and X4 T cell tropic as well as dual tropic viral infections." (PMID 16109172, 2005). "However, the specific mechanism of CXCR4’s role in viral infections remains to be completely clarified." (PMID 41222235, 2025). "Thus, the dual nature of CXCR4 as both a viral receptor and a chemokine receptor not only presents a biological paradox but also a potential new therapeutic strategy for combating viral diseases." (PMID 41222235, 2025). "For example, the DMS assay measuring the binding affinity of a cell surface protein, CXCR4, to its natural ligand has high compatibility with the AS experiment also measuring this ligand binding but has low compatibility with the study on CXCR4’s ability to facilitate virus infection." (PMID 37721410, 2023).